MTDH (metadherin)
Diseases named in the same sentence as MTDH in open-access papers (continued):
Sharing a sentence is not in itself a finding about the gene and the disease.
cancer (continued). "We also examined the effect of MTDH on cell proliferation in DCIS and cancer, and we found that MTDH overexpression was significantly correlated with high Ki67 index (p = 0.008 and p = 0.036, respectively)." (PMID 20565850, 2010). "The immunohistochemical results showed almost no staining in normal tissue, moderate staining in ADH and UDH, intense MTDH stains in DCIS and cancer." (PMID 20565850, 2010). "Metadherin (MTDH), also known as astrocyte elevated gene 1 (AEG-1), is located at chr8q22.1 and functions as a metastatic adhesion protein, making it a therapeutic target in various cancers." (PMID 38977630, 2024). "MTDH protein expression in CRC tissues is considerably higher than that of normal tissues and may suppress the anti-cancer effects of miR-182-5p in CRC cells." (PMID 37438760, 2023). "MTDH plays major roles in stimulation of a group of signaling pathways, such as PI3K/AKT, Wnt/ β-catenin, NF-κB and MAPK cascades, which play a major role in cancer multiplication, aggression, angiogenesis, metastasis and chemoresistance." (PMID 36348199, 2023). "MTDH has been reported to be involved in regulating the activation of several key proteins involved in signalling pathways including Akt, MAPK, NF-κB and β-catenin, which possibly contribute to chemotherapy resistance in cancers." (PMID 34893064, 2021). "Based on the known functions of MTDH and RKIP and our results, the two proteins could be functionally connected during cancer progression." (PMID 33802672, 2021). "Patients with cancer and MTDH-high expression trended to be non-responder or progressive disease (PD)." (PMID 34622157, 2021). "This suggests that MTDH negatively regulates the transcription of the RKIP gene, which could be a target for the development of new cancer therapy." (PMID 33802672, 2021). "Immune checkpoint blockade (ICB) persistently provides a prognosis improvement but only in a small fraction of patients with cancer due to immunotherapy resistance induced by the consecutive activated oncogenic pathways, including MAPK, Akt, and WNT pathway partially driven by Metadherin (MTDH)." (PMID 34622157, 2021). "MTDH, also known as AEG-1, can act as a transcriptional co-factor in cancer signals." (PMID 33802672, 2021). "In conclusion, MTDH and RKIP proteins are important prognostic markers in human cancers." (PMID 33802672, 2021). "What more, the KEGG and GO enrichment assay indicated that MTDH downstream genes also enriched in integrin and collagen binding and PI3K-Akt pathway, which illustrates the potential mechanism of MTDH regulating EMT in a cancer cell." (PMID 34622157, 2021). "We further analyzed four independent cancer cohorts to confirm the negative correlation of MTDH expression with immunotherapy response." (PMID 34622157, 2021). "Indeed, MTDH stimulates EMT and cancer metastasis, and it also exhibits chemoresistance to cancer drugs." (PMID 33802672, 2021). "Furthermore, our analysis illustrated a positive mutual correlation between MTDH expression, EMT score, and m6A RNA methylation in pan-cancer levels, showing a molecular axis from MTDH to m6A RNA methylation and EMT existed in cancer samples." (PMID 34622157, 2021). "The negative correlation of MTDH expression and pooled response rate of immune checkpoint blockade therapy is significant among various cancer types in our preliminary TCGA analysis." (PMID 34622157, 2021). "To confirm whether MTDH confers a mesenchymal-high cell state, we first performed GSEA using TCGA across multiple cancer types." (PMID 31527591, 2019). "Metadherin (MTDH) has emerged in recent years as a crucial mediator of metastasis in several cancer types, although the biological role of MTDH in PDAC has not been investigated." (PMID 29029495, 2017). "Metadherin (MTDH), also known as astrocyte-elevated gene-1 (AEG-1) and LYRIC, is an important oncogene that plays a crucial role in the initiation and progression of most malignant tumors." (PMID 28107197, 2017).
cancer (continued). "Metaherin (MTDH), also called astrocyte elevated gene-1 (AEG-1), is frequently amplified in a variety of cancers, but the roles of MTDH with regard to growth and apoptosis in HCC have not yet been studied." (PMID 26287185, 2015). "In conclusion, our results showed that MTDH expression was significantly increased in HCC cancer tissues compared to matched non-cancerous liver tissues." (PMID 26287185, 2015). "The level of MTDH over-expression is significantly correlated with tumorigenesis, invasion, migration, progression, angiogenesis, EMT (epithelial mesenchymal transition), chemoresistance and radioresistance in various cancer types." (PMID 23240043, 2012). "The expression levels of MTDH is positively correlated with tumorigenesis, migration, invasion, angiogenesis, EMT (epithelial mesenchymal transition) and chemoresistance in various cancer types." (PMID 22195048, 2011). "Additionally, other signaling axes, e.g., signal-regulated kinase (ERK)/mitogen-activated protein kinase (MAPK), Metadherin (MTDH), apurinic/apyrimidinic endonuclease-1 (APEX1), etc., also coordinate with each other to promote cisplatin resistance in different cancers." (PMID 40149331, 2025). "Moreover, there was a significant negative correlation between the MTDH expression and the objective response rate (Pearson coefficient: R = −0.81; p < 0.001), which indicated that high expression of MTDH might associate with poor immunotherapy response in cancer." (PMID 34622157, 2021). "GFWE restored sensitivity to cisplatin by inhibiting MTDH expression, inducing PTEN expression, and improving the interaction between MTDH and PTEN in SKOV3/DDP cells, and these proteins and their interaction may serve as potential targets for cancer treatment." (PMID 32066429, 2020). "However, no studies have reported that MTDH regulates EMT in cancer cells via miRNA regulation network." (PMID 28107197, 2017). "It is possible that with upregulation of MTDH induced by LPS, the secretion of cytokines such as MMPs increased greatly and could degrade the extracellular matrix which then further activated the TLR4 and enhanced the invasive ability of cancer cells." (PMID 22195048, 2011). "However, the ability of MTDH knockdown to sensitize cells to targeted therapies, which have come to symbolize the future of cancer therapeutics, has not yet been explored." (PMID 21687633, 2011). "However, there is no study to investigate the role of MTDH in cancer with ICB treatment." (PMID 34622157, 2021). "In addition, MTDH can function as an effector of multiple epithelial–mesenchymal transition (EMT)-related microRNAs, and incorporate oncogenic signaling pathways such as phosphoinositide 3-kinase-AKT and Wnt/β-catenin to promote EMT, cancer stemness, and metastasis." (PMID 31527591, 2019).
infection (5 papers, 2014 to 2025). The state of being infected such as from the introduction of a foreign agent such as serum, vaccine, antigenic substance or organism. "And the results showed that after infection of MTDH expression vector, cell number and invasion ability recovered." (PMID 29088804, 2017). "Immunofluorescence staining confirmed the nuclear translocation of p65 following MTDH and MTDH-shRNA infection." (PMID 25417825, 2014). "MTDH-shRNA infection or p65-shRNA transfection increased PTEN-Luc activity in SK-BR-3/R cells." (PMID 25417825, 2014). "Furthermore, PTEN-Luc suppression by p65 was enhanced by infection of MTDH." (PMID 25417825, 2014). "Additionally, PTEN-Luc induction by p65-shRNA was enhanced by infection of MTDH-shRNA." (PMID 25417825, 2014). "Of the 227 BRD4 interactors that were recruited to the BRD4 complex during RSV-infection, we observe that 95 ( 42%) are disrupted to some degree by treatment with ZL0454, including most of the transcription factors described in the earlier section (e.g., c-JUN, CTNNB1, JUP, DDX3X, MTDH)." (PMID 33799525, 2021).
MTDH also shares sentences with these, for which no sentence is quoted: esophageal squamous cell carcinoma (9 papers); lung adenocarcinoma (8); metastatic tumors (8); brain tumors (6); renal cell carcinoma (6); colon adenocarcinoma (5); adenocarcinoma (4); retinoblastoma (4); metastasis (3); oral squamous cell carcinoma (3); stomach adenocarcinoma (3); adenoma (2); adenosquamous carcinoma (2); amyotrophic lateral sclerosis (2); astrocytic tumor (2); astrocytoma (2); cervical intraepithelial neoplasia (2); diabetes (2); diabetic cardiomyopathy (2); diabetic kidney disease (2); endometriosis (2); gastric tumor (2); HIV-associated neurocognitive disorder (2); Huntington disease (2); meningioma (2); metabolic dysfunction-associated steatohepatitis (2); neurodegenerative disease (2); neurological diseases (2); oligodendroglioma (2); oral cancer (2).
A further 86 diseases each share a sentence with MTDH in 2 papers or fewer.